NLRP3 (NLR family pyrin domain containing 3)
Diseases named in the same sentence as NLRP3 in open-access papers (continued):
Sharing a sentence is not in itself a finding about the gene and the disease.
diabetes (continued). "Metformin inhibits high glucose-induced TXNIP/NLRP3 inflammasome activation through AMPK activation in macrophages, which suppresses diabetes-mediated atherosclerosis." (PMID 37394581, 2023). "Our study showed that the expressions of NLRP3 inflammasome and other antiviral inflammatory cytokines in the NG group were lower than those in the PDM groups, suggesting that the pre-diabetes is indeed in a chronic inflammatory state." (PMID 36248820, 2022). "Dogma supports NLRP3-induced inflammation as fundamental to changes in glucose tolerance, insulin resistance and inflammation as observed in both type 1 (T1DM) and type 2 diabetes mellitus (T2DM)." (PMID 35755447, 2022). "Therefore, we aimed to explore the effect and potential mechanism of Tai Chi intervention on the NLRP3 inflammasome and its related inflammatory factors in pre-diabetic population, and we seek an economical and effective strategy to alleviate and improve diabetes." (PMID 36248820, 2022). "A previous study from this group showed that the receptor for HCA2 is overexpressed in the retina following diabetes and its activation with the systemically administered compound BHB can reduce the NLRP3 inflammasome activity and reduce retinal damage." (PMID 36077579, 2022). "Diabetes promoted the decrease of LC3-II content, increased the p62, NLRP3, gasdermin-D-N, and IL-18 levels in myocardial tissue." (PMID 36320147, 2022). "Hence, the effect of NLRP3 rs4925650 GA/AA genotypes and NLRP3 rs10157379 CT/TT genotypes on susceptibility to CKD appears to be independent of age, sex, educational level, consumption of tea, alcohol, and coffee, analgesic usage, and disease histories of diabetes and hypertension." (PMID 35428826, 2022). "We performed a correlation heat map analysis to determine the correlation between the intestinal microbiota and diabetes related glucose-metabolism parameters (BW, Liver/BW, FINS, FPG, GSP, HOMA-IR, PBG, and NLRP3)." (PMID 36532503, 2022). "The comorbidity of smoking, hypertension, diabetes, elevated LDL-C and lipoprotein(a), or decreased HDL-C also correlated with increased NLRP3 protein expression in the aorta." (PMID 36438901, 2022). "Accumulating evidence revealed that NLRP3-inflammasome-mediated chronic inflammation contributed to the development and progression of DM and its complications, such as diabetic nephropathy 6, diabetic retinopathy 16,17, diabetic cardiomyopathy 18, and diabetes-associated atherosclerosis." (PMID 35002527, 2022). "In the present study, the effect of endurance training on the expression of NLRP3, P38 MAPK, TNF-α, and IL-1β genes in the spinal cord of rats with diabetic neuropathic pain was investigated." (PMID 35655729, 2022). "Aerobic exercise is believed to be a promising intervention to reduce the expressions of ROS, NF-κB, NEK7, NLRP3, ASC, Caspase-1, IL-1β, and other inflammatory factors, and improves diabetes-induced inflammation and reduces insulin resistance." (PMID 36248820, 2022). "Sulforaphane has reportedly undergone testing in NLRP3 inflammasome-related disorders like osteoarthritis, COPD, AMD, diabetes, and cardiovascular disease." (PMID 34443594, 2021). "In conclusion, vaspin inhibited obesity- and diabetes-related ER stress enhancement, autophagy impairment, LMP, NLRP3 inflammasome activation in PTCs and subsequent cell death." (PMID 33742129, 2021). "Several lines of evidence have revealed that diabetes-induced renal NLRP3 inflammasome activation, TGF-β1/Smad3 activation, and ECM protein accumulation were inhibited in NLRP3 knockout mice." (PMID 34504642, 2021). "Evidence has shown that the NLRP3 inflammasome, IL-1β, thioredoxin-interacting protein (TXNIP), and pyroptosis play vital roles in the development of diabetes." (PMID 34356130, 2021). "This indicated that the decreased NLRP3 inflammasome activity in NAG-1 Tg mice alleviates diet-induced obesity and enhances insulin sensitivity in the HFD/STZ-induced diabetic mouse model." (PMID 34294853, 2021).
diabetes (continued). "The activation of diabetes-mediated related factors such as TLR4, NLRP3, caspase-1, IL-1β, IL-18, and GSDMD-NT plays a vital role in the pathophysiology of DKD." (PMID 33692782, 2021). "The evidence has shown that the NLRP3 inflammasome, IL-1β, thioredoxin-interacting protein (TXNIP), and pyroptosis play vital roles in the development of diabetes." (PMID 31835423, 2019). "However, it is unknown whether NLRP3 inflammasome plays an essential role in stroke in diabetes." (PMID 29853850, 2018). "The diabetes-induced upregulation of VEGF and proteins in the TXNIP/NLRP3 pathway was prevented by vitamin D3 treatment." (PMID 29682582, 2018). "In this study, we selected the autophagy/mitophagy-related protein, NLRP3, and its downstream molecule IL-1β, to explore the liver-protective effect of Exe on HFD-induced NAFLD and diabetes in C57BL/6 mice." (PMID 29849583, 2018). "A number of small molecule inhibitors have been identified that inhibit NLRP3 inflammasome activation, for example, MCC950 and the diabetes drug glyburide." (PMID 28192528, 2017). "During the progression of diabetes, CB1 promotes the Nlrp3-ASC inflammasome activation and the release of IL-1β and IL-18 in infiltrating macrophages, which act as paracrine signals to induce beta cell apoptosis." (PMID 29033935, 2017). "When compared with the control rats, diabetic rats showed elevated mRNA and protein levels of NLRP3, ASC, caspase-1 and IL-1β beginning at 4 or 8 weeks of diabetes (all p<0.01)." (PMID 25136835, 2014). "Klotho, which mitigates diabetes-induced elevation of serum creatine kinase-muscle/brain (CK-MB) and LDH, cardiac fibrosis, cardiomyocyte apoptosis, and cardiac dysfunction, also inhibits NLRP3 activation and TNF-α, IL-1β, and IL-18 expression." (PMID 41399377, 2026). "In summary, aerobic exercise can alleviate diabetes and PDM by inhibiting NLRP3 inflammasome." (PMID 41264598, 2025). "Genetic polymorphisms in NLRP3, NLRP1, or IL−1β genes influence individual inflammatory responses, and not all patients—especially in diabetes—display inflammasome-driven pathology." (PMID 41488670, 2025). "Diabetes positively regulates APP (4 references; q = 0.00015), NLRP3 (19 references; q = 0.00168), and PVT1 (4 references; q = 0.00755), while negatively regulating CYP2C19 (14 references; q = 0.00372), suggesting its influence on pathways related to inflammation, immune response, and metabolism." (PMID 40881172, 2025). "The literature has not fully explored the causal relationship between NLRP3 inflammasome activation and T2DM, and how this activation affects diabetes progression and response to therapy." (PMID 39717099, 2024). "The systematic review results confirm that diabetes impairs the transformation of fibroblasts into myofibroblasts by affecting the expression of several growth factors, most notably transforming growth factor beta (TGF-beta) and NLRP3." (PMID 39201678, 2024). "The NLRP3/GSDMD axis was shown to modulate pyroptosis and inflammation in pancreatic β cells during hyperglycemia, implying the role of GSDMD in promoting the progression of diabetes mellitus." (PMID 39253076, 2024). "Subgroup analysis showed that no substantial interactions occurred between serum NLRP3 levels and other variables, such as age, gender, hypertension, diabetes mellitus, primary renal diseases, and MACCE (all P > .05)." (PMID 39093762, 2024). "A similar NLRP3-dependent dysregulation of PGF2α release was anticipated, but it is unclear why diabetes does not impact PGF2α release in this model." (PMID 38682210, 2024). "Unlike WAT IL-1β-secretion, the expression of WAT NLRP3 and to a lesser extent IL1B was positively associated with all diabetes risk factors examined with no group-differences." (PMID 37914804, 2023). "Although exercise was able to inhibit the overactivation of NLRP3 inflammasome in human models of T2DM, healthy young students, elderly subjects, and obese children, few studies have focused on pre-diabetes." (PMID 36817440, 2023).
diabetes (continued). "When the inflammatory parameters were re-evaluated according to the presence of concomitant diabetes, lower levels of IL-18 and hsCRP were detected in the presence of diabetes, but no significant change was observed in the NLRP3 and IL-1β levels." (PMID 37763063, 2023). "However, another study reported that the reduction of the NLRP3 inflammasome by MCC950 resulted in a considerable amount of renal inflammation and injury in the model of diabetic kidney mice." (PMID 38114914, 2023). "Moreover, it has been shown that the activation of NLRP3 inflammasome in the diabetic retina elicits a prolonged inflammatory response and BRB injury in an experimental model of diabetes." (PMID 37372968, 2023). "Hence, we concluded that NLRP3 inflammasome in the diabetic kidneys of the modified DKD rat model is activated, and FPS, similar to RAP, can inhibit NLRP3 inflammasome activation in vivo and in vitro." (PMID 35370636, 2022). "This drug was able to improve glucose homeostasis in diabetic mice, although its pharmacological application at the moment is mostly oriented to the management of diabetes rather than the NLRP3-mediated over-inflammation." (PMID 35204152, 2022). "A study identified that the RBP TTP could inhibit NLRP3 expression in human macrophages by targeting the AU-rich elements in the NLRP3 3′- UTR, which might influence the development of diabetes." (PMID 35597446, 2022). "Therefore, 12 weeks of Tai Chi intervention can significantly decrease the expressions of NEK7, NLRP3, ASC, Caspase-1, GSDMD, IL-1β, and IL-18, while increasing the expression of irisin in pre-diabetes." (PMID 36248820, 2022). "This can be the case for metabolic diseases, such as metabolic syndrome, obesity, and type 2 diabetes mellitus (T2DM), as well as some auto-inflammatory disorders, which may benefit from IL-1β blockers, or even NLRP3 inflammasome inhibitory therapies." (PMID 35111374, 2022). "Immunohistochemical fluorescence assay revealed that the levels of NLRP3, ASC, and GSDMD were significantly increased in the ApoE−/− mice following induction of diabetes and consistent feeding with a Western diet compared with the ApoE−/− mice fed with a control diet." (PMID 36425580, 2022). "In DKD, the renal NLRP3 protein amount was significantly higher compared to kidney samples from patients without diabetes." (PMID 35204131, 2022). "Dapagliflozin, an SGLT2 inhibitor, has been shown to reduce renal injury even in the absence of diabetes, through inhibition of the NLRP3 inflammasome, protecting against kidney fibrosis." (PMID 35755447, 2022). "In addition to diabetes, ischemic stroke, and acetaminophen (APAP)-induced liver disease, the ROS/NLRP3 pathway plays a major role in some kidney diseases." (PMID 35656447, 2022). "We also already highlighted the increased renal tissue gene expression of NLRP3 in hypertensive/vascular nephrosclerosis in the absence of diabetes." (PMID 35204131, 2022). "In this study, we explored whether ROS-induced NLRP3 inflammasome priming and activation were related to PCB118 exposure in mouse islet β-TC-6 cells and the mechanisms of diabetes." (PMID 34055976, 2021). "To investigate whether ISO offers retinal protection against stroke-induced retinal injury in diabetes, we administered ISO prior to middle cerebral artery occlusion (MCAO) in diabetic mice and studied the role of NLRP3 inflammasome activation in the retina." (PMID 34305534, 2021). "Overall, we characterize the corresponding role of diabetes in CCS and speculate a link of NLRP3 inflammasome between them." (PMID 34512671, 2021). "It has been previously proved that NLRP3 inflammasome-mediated HMGB1 release plays a vital role in endothelial hyperpermeability during several metabolic disorders such as obesity, hyperglycemia, and diabetes." (PMID 34838052, 2021).
diabetes (continued). "Whether ERS can activate NLRP3 inflammasome through the ROS/ERK1 pathway or NF-κB pathway and whether NLRP3 inflammasome can regulate ERS in diabetes deserved to be studied." (PMID 33937267, 2021). "A previous review has discussed NLRP3 inhibitors however, the authors did not summarize the literature in natural herbal products on NLRP3 inflammsome especially pertinent to diabetes." (PMID 34631209, 2021). "Numerous studies have revealed that activation of NLRP3 inflammasome in macrophages cells can sniff cellular damage and modulates inflammatory responses in cognitive impairment, ALI, cancer, renal disease, liver disease, and diabetes mellitus." (PMID 34599154, 2021). "However, this is the first evidence that TXNIP is directly required for NLRP3-inflammasome activation and retinal microvascular dysfunction in a model of HFD-induced insulin resistance and pre-diabetes." (PMID 32492941, 2020). "The excessive production of mROS can activate the NLRP3 inflammasome through the TRX/TXNIP, but the function of this signal pathway in diabetes pathway remains unknown." (PMID 32175320, 2020). "Our findings provide new insights into the understanding of NLRP3 inflammasome-initiated HASMC calcification under high glucose stimulation and indicate a potential pharmaceutic role of 6-shogaol in cardiovascular complication of diabetes." (PMID 31938471, 2020). "This review summarizes the regulation of type 1 diabetes mellitus (T1DM) and type 2 diabetes mellitus (T2DM) by NLRP3 via modulation of glucose tolerance, insulin resistance, inflammation, and apoptosis mediated by endoplasmic reticulum stress in adipose tissue." (PMID 31835423, 2019). "Unfortunately, there is a lack of clinical studies regarding NLRP3 inflammasome-specific treatment in patients with diabetes complicated with stroke." (PMID 31174550, 2019). "In summary, the present study shows i) overexpression of retinal HCA2 with diabetes; ii) increased levels of retinal BHB after systemic administration; iii) reduced ER stress after BHB; iv) reduced NLRP3 inflammasome activity after BHB; and finally, v) reduced retinal damage." (PMID 30657794, 2019). "Currently, NLRP3 drug development for the treatment of diabetes and stroke is still in the initial stage and no selective NLRP3 blockers are available in a clinical setting." (PMID 31174550, 2019). "NLRP3-inflammasome activation and its role in the progression of heart failure in the absence of diabetes is well-described." (PMID 29515457, 2018). "Exe may reduce oxidative stress injury and inhibit the NLRP3 inflammasome by enhancing the autophagy/mitophagy pathway in liver, which has a protective effect on the liver in NAFLD and diabetes in C57BL/6 mice." (PMID 29849583, 2018). "NLRP3- and IL-1R-deficient mice, but not ASC-deficient mice, showed reduced incidence of diabetes, less insulitis, lower hyperglycemia, and normal insulin levels compared to wild-type (WT) diabetic mice." (PMID 28289409, 2017). "Although the role of NLRP3 inflammasome activation in diabetes has been demonstrated, the molecular targets utilizing high glucose during NLRP3 inflammasome activation in macrophages are not well understood." (PMID 28164132, 2017). "AS and type 2 diabetes mellitus (T2DM) are metabolic diseases and share similar pathophysiological mechanisms, including NLRP3 (nucleotide-binding domain, leucine-rich-containing family, pyrin domain-containing-3) inflammasome activation, which has been highlighted in recent studies." (PMID 29151018, 2017). "In the development of glucotoxicity in diabetes, endogenous glutamate aggravates the high-glucose-induced β-cells dysfunction via excessive activation of NMDA receptors on β-cells, leading to activation of NF-κB and NLRP3 inflammasomes." (PMID 28303894, 2017). "The NLRP3 inflammasome activation and subsequent maturation and secretion of IL-1β and IL-18 initiated further pro-inflammatory events, producing kidney damage of STZ-induced diabetic rats." (PMID 22701621, 2012).
diabetes (continued). "In diabetes-induced renal injury, caffeic acid protects renal function by reducing serum creatinine and blood urea nitrogen and inhibiting the production of inflammatory cytokines (such as IL-1β, IL-18, IL-6, and TNF-α) and the expression of NLRP3 inflammasome." (PMID 40909020, 2025). "The consistent directionality and statistical significance observed in the regulation of APP, NLRP3, PVT1, and CYP2C19 suggest the possibility of a Diabetes → gene → HNSCC pathway, in which diabetes-related gene alterations may contribute to HNSCC pathogenesis." (PMID 40881172, 2025). "Also, there were no marked interactions between serum NLRP3 levels and age, gender, hypertension, diabetes mellitus, primary renal diseases, and MACCE (all P > .05)." (PMID 39093762, 2024). "Interestingly, diabetes does not affect the amount of PGF2α released from urothelia and detrusors regardless of the presence or absence of the NLRP3 gene." (PMID 38682210, 2024). "FGF21 protects the vascular endothelium and smooth muscle layers by inhibiting the NLRP3 inflammasome, and our previous research showed that FGF21 inhibits VSMC proliferation and migration through inhibition of the SYK-NLRP3 inflammasome pathway, alleviating diabetes-induced neointimal hyperplasia." (PMID 38733164, 2024). "In the absence of NLRP3, diabetes does not impact expression of either FP receptor isoform." (PMID 38682210, 2024). "However, to the best of our knowledge, there was no study that reported the effect of ST on the hepatic NLRP3, caspase-1, and IL-1β in diabetes rat models induced by STZ, which emphasizes the importance of this study." (PMID 38131990, 2023). "The regulating Forkhead box O3a (FOXO3a) acetylation by p300 is another mechanism involved in diabetes-induced inflammation: diabetes-induced FOXO3a acetylation prevents its binding to gene target promoters, increasing NOD-, LRR- and pyrin domain-containing protein 3 (NLRP3) inflammasome activation." (PMID 36766773, 2023). "Finally, we propose several promising targeted NLRP3 inflammatory vesicle inhibitors with the aim of providing a basis for NLRP3-targeted drugs in diabetes combined with noncoronary pneumonia in the clinical management of patients." (PMID 37868953, 2023). "In addition, our data demonstrate that diabetes induced increased expression of NLRP3 inflammasome components pro-caspase 1 and NLRP3 were not significantly attenuated by MCC950." (PMID 35048962, 2022). "Therefore, in the present study, CRAMP may inhibit the activation of colonic MyD88/JNK/NF-κB/NLRP3 signaling pathway, subsequently suppressing the recruitment of IFN-γ+ T cells and their migration to the pancreas in C. rodentium-accelerated diabetes." (PMID 35547774, 2022). "For example, increased circHIPK3 stimulated the activation of the TLR4 pathway and NLRP3 inflammasome and the production of pro-inflammatory cytokines (e.g., TNF-α, IL-1β) in gouty arthritis whereas its silencing alleviated inflammatory damage in myocarditis and diabetes mellitus." (PMID 36072601, 2022). "However, the functional effect of MFG-E8 on “NLRP3 inflammasome-NETs” inflammatory loop in wound healing of diabetes is not completely elucidated." (PMID 32963812, 2020). "Therefore, we investigated whether LBE has ameliorating effects on renal damage by suppressing NLRP3 inflammasome-related hyperinflammation and activating AMPK/SIRT1/PGC-1α signaling in type 2 diabetes mellitus (T2DM) mice." (PMID 32050658, 2020). "By contrast, in diabetes and its complications, while the inflammatory process may not be easily reversible, targeting the NLRP3 inflammasome as an early preventive strategy may prove beneficial." (PMID 31174550, 2019). "NLRP3, caspase-1, IL-1β, and IL-18 were minimally expressed in normal glomerular tissues, but were significantly up-regulated in diabetic apoE (-/-) and apoE (-/-) mice, with more prominent changes in diabetes apoE (-/-) mice." (PMID 28708885, 2017).